XCR1 (X-C motif chemokine receptor 1)
Diseases named in the same sentence as XCR1 in open-access papers (continued):
Sharing a sentence is not in itself a finding about the gene and the disease.
tumor (continued). "This would be compatible with an infiltration by immature peripheral DCs originating from the ventricles of the depth of the tumor and their differentiation into XCR1+/MHCII+ phenotype along their migration through the tumor toward the meninges." (PMID 27193333, 2016). "Fluorescent invading cells were conventional XCR1+ and monocyte-derived dendritic cells distributed in subpopulations of different maturation stages, located in different areas relative to the tumor core." (PMID 27193333, 2016). "MHCII immunostaining indicated that XCR1+ DCs were exclusively located in the meninges and superficial tumor areas at D21 then accumulated at the tumor margins by D28." (PMID 27193333, 2016). "Multiplex immunofluorescence analysis revealed that TLR7 was significantly upregulated by IFNα therapy in cells expressing myeloid cell markers such as CD1c+, CD68+ and CD141+ and in XCR1+ cells, a marker specific for type I DCs in the tumor and the surrounding stroma." (PMID 39849091, 2025). "In the viral cytokine receptor pathway, upregulated genes (p = 1.39 × 10−5), including TNFRSF1A, CCL21, IL2RB, IL22RA1, and XCR1, suggest that oncolytic viruses exploit tumor-specific immune evasion mechanisms to selectively lyse tumor cells, activating anti-tumor immunity via DAMPs and PAMPs." (PMID 40406701, 2025). "Moreover, knockdown of XCR1 was shown to markedly enhance tumor cell proliferation and migration while dampening apoptosis." (PMID 39835121, 2024). "Immunohistochemical validation of tissue samples from CRC patients was showed that mildly positive CCR10 and XCR1 expression could be observed in tumor tissues, but higher CCR10 and XCR1 expression was observed in normal tissues." (PMID 39835121, 2024). "Among 28 chemokine genes available, CXCL9/10/11/CXCR3, CXCL13/CXCR5 and XCL1/XCR1 mRNA expression were significantly increased in RCC compared to normal kidney tissue and also strongly associated with tumor-infiltrating effector memory and central memory CD8+ T cells in all investigated collectives." (PMID 37006314, 2023). "Thus, based on these findings and the enrichment of XCR1 expression on tumor DCs compared to non-tumor DCs in humans and mice, XCR1 was selected as the cDC1 target." (PMID 37942313, 2023). "Furthermore, the XCR1+ cDC1 cell subset cross-presents antigen and primes anti-tumor CD8+ cytotoxic lymphocytes." (PMID 37024121, 2023). "Moreover, CCL5 and XCL1 produced by tumor-infiltrating NK cells and innate lymphoid cells promoted the recruitment and activation of XCR1+ cDC1s, fostering NK-cDC1 axis-related control of tumor growth." (PMID 36949244, 2023). "In the tumor, XCR1 detection was also decreased in mice treated with the high dose of the XCR1Ab-IFNL53A fusion (10 mg/kg) compared to the isotype control, which correlated with a significant gain in IFN activity in cDC1s, based on greater PD-L1 and CD86 expression." (PMID 37942313, 2023). "Indeed, IL-33 expression correlated strongly with CD8A and granzyme B as well as genes like BATF3, IRF8, THBD, CLEC9, and XCR1 that are required for tumor antigen cross-presentation functionality of CD103+ dendritic cells (DCs)." (PMID 36256464, 2022). "Additionally, we found that CD39i treatment increased the proportion of tumor infiltrated cDC1, XCR1 + cDC1 as well as the tumor Xcl1 protein levels in control mice, but not in NK cell absent mice." (PMID 36347860, 2022). "Complementing the hypothesis that cDC1s migrate in the tumor through the XCL1/2 – XCR1 axis, we show that, besides for NK-cells, XCL1/XCL2 were also expressed by a subpopulation of ENTPD1+ ITGAE+ CD8+ T-cells." (PMID 36741389, 2022). "In addition, it has recently been reported that activated CD8+ T cells and NK cells secrete XCL1 and attract XCR1-expressing cDC1s to the tumor microenvironment." (PMID 34885241, 2021). "Research by He's research group indicated the interleukin (IL) 10, together with XCR1 might be a key regulator for the tumor microenvironment of ccRCC." (PMID 33377624, 2021).
tumor (continued). "These markers may become a substitute or a supplement for tumor XCR1 expression as the tumor antigen-presentation-related marker." (PMID 34230534, 2021). "As a result, our study demonstrated that XCR1, a potential prognostic biomarker for ccRCC, could decrease tumor cell proliferation and migration, and increase apoptosis." (PMID 33377624, 2021). "Recently, the discovery of X-C Motif Chemokine Receptor 1 (XCR1) as a specific and conserved marker of cross-presenting DC has allowed for the specific targeting of these subsets as a strategy to direct productive anti-tumor immunity." (PMID 34944809, 2021). "Importantly, we further observed that TNFSF13B, CASP5 and XCR1 showed the remarkable correlations with tumor‐infiltrating immune cells." (PMID 32311223, 2020). "However, the numbers of cDC1 were significantly less and the intensities of CD11c, CD103 and XCR1 were significantly lower in lung tumors from KP7 mice than KP mice at 10 weeks after tumor induction." (PMID 33257678, 2020). "Additionally, studies specifically addressing the nature of DC subsets responsible for cross-presenting peripheral tumor antigens have evidenced migratory XCR1+ DC as responsible for priming CTL responses." (PMID 32075343, 2020). "In murine models, XCR1+ DCs, present in lymph nodes and peripheral tissues, have been postulated as potent target candidates for induction of cytotoxic T cell responses 41 and anti-tumor immune responses." (PMID 31534520, 2019). "In addition, the result showed that both IL10 and XCR1 were closely related to the infiltration of tumor immune cells (Supplemental )." (PMID 31781309, 2019). "Specifically, murine CD8a+CD103+BATF3+CLEC9A+XCR1+ cDC1s have been demonstrated to have a critical role in the cross-presentation of tumor antigens and are generally thought to be indispensable in the development of host anti-tumor immune responses." (PMID 31921140, 2019). "Importantly, LTX-315 cooperates with RT to promote tumor infiltration by XCR1+ DCs, which are essential for induction of anti-tumor immunity." (PMID 30400822, 2018). "Comparing sham-operated and tumor-bearing mice at D28, we observed significant increases in T lymphocytes (three-fold increase), natural-killer cells and in all DC subpopulations (XCR1+ DCs, CD11b+ DCs and plasmacytoid DCs, monocyte-derived DC P2 and P3 as well as in their precursor P1)." (PMID 27193333, 2016). "XCR1 overexpression could inhibit liver cancer cells’ proliferation, and promote tumor migration." (PMID 33377624, 2021). "Cells in the DC-C1 cluster, characterized by high expression of XCR1 and IRF8, were identified as conventional type 1 dendritic cells (cDC1s) and were predominantly enriched in NMI tumour samples." (PMID 41281745, 2025). "To investigate the distribution of intratumoural cDC1s during CD8+ T cell priming and expansion within tumours, we inoculated MCA205 LA‐OVA‐mCherry cells in Xcr1‐Venus mice and harvested tumours on days 6 and 9 postimplantation." (PMID 40745918, 2025). "Due to the interaction between XCL1 in CD8+ T cells and XCR1 in DCs playing the key role in anti-tumor efficacy, the number of XCL1+ CD8+ T cells and XCR1+ DCs in microenvironment directly determined the prognosis of HCC patients." (PMID 41426973, 2025). "In vivo, PIB adenoviruses transformed tumor cells into cDC1-like cells, which expressed immunogenic markers (MHC I/II, CLEC9A, XCR1) and attracted T cells to the TME." (PMID 39820487, 2025). "The main problem for playing the anti-tumor role of XCL1+ CD8+ T cells is the low expression of XCL1 and key related genes (XCR1 and XCL2) in tumor microenvironment of HCC." (PMID 41426973, 2025). "This warranted further study as cDC1s are a cDC subtype which expresses XCR1 and is involved in cross-presentation and CD8+ T cell-mediated anti-tumor responses." (PMID 38942798, 2024).
tumor (continued). "Aside from improving the quality and number of tumor‐infiltrated CD8+ T‐cells, combination therapy also increased the population of inflammatory DC (CD11c+Ly6c+), CD103+ DC and XCR1+ DC." (PMID 38400597, 2024). "Injection of DT into XCR1-DTR mice induced cDC1 depletion in the whole body, not only within the tumor." (PMID 39474418, 2024). "We found that a single treatment with the anti-XCR1 Ab and IFN mutein (XCR1Ab-IFNmut) fusion specifically enhanced cDC1 activation in the tumor and spleen compared to untargeted control." (PMID 37942313, 2023). "Analyses of hot tumors have revealed that cDC1 (CD24+XCR1+ DCs in mice, CD141+ XCR1+ DCs in humans) tumor-infiltrating dendritic cells (TIDCs) recognize tumor-derived DNA in the cytoplasm via cGAS." (PMID 37046775, 2023). "In conclusion, we produced a recombinant human XCR1 agonist (XCL1(CC3)) and developed a strategy to conjugate it to a poorly soluble epitope of a clinically relevant tumor antigen." (PMID 35428705, 2022). "When Xcr1-Cre was used to delete either MHC-II or CD40, tumor rejection was severely reduced, which suggests that a cognate interaction between CD4 T cells and cDC1s is required, at least to realize the full effect of CD8 T cell priming." (PMID 34480145, 2022). "Mice given unmodified Neo-LNP showed a significant increase in CD69+ tumor-infiltrating T cells and the expression levels of CD40 in cDC1 (CD11c+ XCR1+)." (PMID 36311701, 2022). "Activated NK cells secrete several chemokines, such as CCL4, CCL5 and XCL1, that are responsible for the recruitment into the tumor of CCR5- and XCR1-expressing cDC1s." (PMID 34975880, 2021). "The conventional type-1 DC (cDC1) expresses the chemokine receptor XCR1 and CD103 and lower amount of CD11b that has the high ability to migrate from tumors to lymph nodes and presents a tumor antigen to CD8+ T cells." (PMID 34751648, 2021). "We further found that the numbers of CD11c+CD11b−CD103+H-2Kb+ DCs which expressed high levels of CD86, XCR1 and CD24 but low levels of CD64 were significantly reduced in tumor-burdened lungs of KP7 mice compared to KP mice." (PMID 33257678, 2020). "Tumor-derived VEGF subverts NK cell function by blocking Flt3L, profoundly impacting XCR1+ DC development and function." (PMID 32121071, 2020). "In accordance with this, the administration of IFNα-producing iPSC-derived proliferating myeloid cells (pMCs) to mice strongly activated host CD141+XCR1+ DCs, enhancing their CD8+ T cell priming capacity and thus boosting anti-tumor immune responses." (PMID 32075343, 2020). "For instance, Xcl1 or an anti-Xcr1 mAb have been fused to the full OVA protein and tested in antitumor vaccinations, albeit in a tumor prophylaxis setting." (PMID 30863405, 2019). "Alongside the two classical cross-presenting populations that are CD8+XCR1+ and CD103+XCR1+ we have previously identified populations of LN-resident CD8−XCR1+ DCs and migratory CD103−XCR1+ DCs that are able to cross-present tumor antigen." (PMID 30700986, 2018). "The discrepancy between the recent and earlier studies is likely due to XCR-1, but not Batf3 or CD11c, being specifically expressed by cDC1s; Baft3 and CD11c expression by certain non-cDC1 cells likely impacts anti-tumor immunity." (PMID 40227734, 2025). "Xcr1+ type 1 conventional dendritic cells (Xcr1+ cDC1) (also known as CD8+ DC or CD103+ DCs) has been recognized for their role in cross-presentation and activating naive CD8+ T cells, and are critical for anti-viral and anti-tumor immune responses." (PMID 40934103, 2025). "Furthermore, the combination therapy increased migratory XCR1+CD103+ dendritic cells (DCs) in tumors and tumor-draining lymph nodes (TDLNs) while expanding CD44+CD8+ T cells with central and effector memory phenotypes." (PMID 40366419, 2025). "To demonstrate the on-target effects of anti-CCR3 antibody, we also evaluated the immunogenicity and anti-tumor effect of XCL1-E6E7 with XCR1 as the specific receptor in mice with or without CCR3 + cells." (PMID 38459592, 2024).
tumor (continued). "On the other side, tumor cells counteract this axis by releasing PGE2, a molecule that concomitantly inhibits NK cell functionality and DC recruitment via X-C Motif Chemokine Receptor 1 (XCR1) and CCR5 downregulation." (PMID 37298470, 2023). "Similarly, the upregulation of CCR7, XCR1, MHC-II molecules and CD86 on cDC1 was observed upon BCL2 inhibition with venetoclax in the MCA205 tumor model." (PMID 37623817, 2023). "However, these samples observed different stromal and tumor enrichments for CD4+ T cells, cDC1s, and XCR1+CD163+ cells compared to CRC1." (PMID 37731497, 2023). "In addition to promoting increased lymphocytic infiltration into the TME, TPST-1495 treatment also resulted in an increase in the numbers of XCR1+ DC1 cross-presenting dendritic cells, as a proportion of total cells within the tumor." (PMID 37559947, 2023). "We next validated that XCR1+CD163+ cell types could be found in other colorectal (CRC2) and kidney (KID1) tumor samples subjected to Cyclone." (PMID 37731497, 2023). "XCR1 downregulation has been shown to stimulate the immune system to exert the antitumor activity, which is critical to alter the immune cell landscape in the TME that delays tumor progression." (PMID 35356506, 2022). "Regardless, tumor-specific T cells expanded in the absence of Xcr1, suggesting that cDC1s that lack Xcr1 still elicit tumor-specific T cells." (PMID 35393950, 2022). "cDC1, cDC2, XCR1-CD11b double negative (DN) cDCs and pDCs all increased in the tumor, with cDC1s accounting for the largest proportion of accumulated DCs in the TdLN." (PMID 36418317, 2022). "Based on data from the TCGA, we found that from stage I to III, with tumor progression, the expression of XCR1 slightly increased; however, there was no statistical difference in the overall trend." (PMID 33377624, 2021). "In fact, the combination of blood-based tumor mutational burden and multiple chemokines may also be useful for predicting the efficacy as a substitute for the combination of XCR1 and CXCR3 ligands in the tumor." (PMID 34230534, 2021). "DCs were further subdivided into cDC1 (cross-presenting dendritic cells; cluster 5 in Paratumor and cluster 11 in Tumor; CLEC9A+ and XCR1+), cDC2 (cluster 1 in Paratumor and cluster 1 in Tumor; CD1C+) and plasmacytoid DC (pDC; cluster 4 in Paratumor and cluster 13 in Tumor; LILRA4+ and IL3RA+)." (PMID 33429363, 2021). "Transcriptomics and proteomics analyses revealed complex effects on the tumor microenvironment triggered by hetIL-15 therapy, including increased levels of IFN-γ and XCL1 with intratumoral accumulation of XCR1+IRF8+CD103+ conventional type 1 dendritic cells (cDC1)." (PMID 32461349, 2020). "Considering the ideal characteristics of DCs for eliciting a strong anti-tumor immune response referred to above, cDC1, particularly CD141+XCR1+ DCs (the homologues of murine CD8α+ DCs), besides being highly proficient in executing cross-presentation, produce large amounts of IL-12 and IL-15." (PMID 32075343, 2020). "Consistently with these observations, the numbers of infiltrating cDC1 and the intensities of CD11c, XCR1 and CD8 staining were significantly increased in the tumor-burdened lungs of KP or KP7 mice injected with CCL7 compared to those injected with control viruses." (PMID 33257678, 2020). "Thus, like monoclonal antibodies against an endocytic receptor such as DEC205,17,18 XCL1-based targeting through XCR1 can mediate Ag processing and presentation, thereby leading to CD8+ T-cell responses against tumours." (PMID 32066911, 2020). "Here, we have discussed the XCR1+ cross-presenting subset as a potential focus of next-generation DC therapies, due to their specialized ability to prime effector CD8+ T cells and role in mediating anti-tumor responses." (PMID 32121071, 2020). "XCR1 (X-C motif chemokine receptor 1) and XCL1 (X-C motif chemokine ligand 1) had been reported to enhance proliferation of antigen-specific CD8+ T cells and their anti-tumor immunity." (PMID 33043022, 2020).
tumor (continued). "In this context, we aimed to target to Xcr1+ DCs tumor antigens in the form of SLP genetically fused or not to the Xcl1 chemokine." (PMID 30863405, 2019). "In addition, the co-stimulatory molecule CD86 was upregulated in both CD11c+MHC-IIhiCD26+XCR1+CD172a− cDC1 and CD11c+MHC-IIhiCD26+CD172a+XCR1− cDC2 in the tumor-draining lymph node." (PMID 31694706, 2019). "Because XCL1, the ligand for the chemokine receptor XCR1 expressed by cDC1, was not represented in the protein or the cytometric bead arrays, we analyzed tumor extracts for Xcl1 mRNA." (PMID 29429633, 2018). "In humans, equivalent BAFT3 dependent DCs are identified by the expression of CD11c, CLEC9A, XCR1 and CD141, have been found in different tumor types and, just as the murine DC, seem to be relevant in anti-tumor responses, since their presence correlates with a superior outcome in melanoma patients." (PMID 29050360, 2017). "Because there are fewer chemokine receptors than chemokine ligands, we first assessed the levels of expression of mRNAs encoding all 18 types of chemokine receptors (CXCR1-6, CCR1-10, XCR1, and CX3CR1) in the inflammatory cells located around the tumor in our patient." (PMID 25123545, 2014). "The superior activation of CD4+ and CD8+ T cells could be induced by a higher frequency of migratory cDC1s (XCR1+ CD103+), which possess the unique ability to transport tumor antigens to lymphoid structures and excel at cross-presenting the TAAs to CD8+ T cells." (PMID 39703517, 2024). "Indeed, also in flow cytometric analysis CD81+migcDC1s could be identified by their distinct expression of CD81 and XCR1 and were significantly increased upon Flt3L treatment in the E0771, TS/A and LLC tumor models." (PMID 37622122, 2023). "viSNE analysis revealed that NDV-killed tumor cells preferentially induced activation of Lin-I-Ad+CD11c+ conventional DCs (cDCs), as indicated by upregulation of MHC II, co-stimulatory molecules (CD86, CD40) and PDL1, with similar effects in both cross-presenting XCR1+ cDC1 and CD11b+ cDC2 subsets." (PMID 36418317, 2022). "COX-2/PGE2 can also inhibit the secretion of CCL5 and XCL1 by natural killer (NK) cells and the expression of CCR5 and XCR1 in conventional type 1 dendritic cells (cDC1), which can impair the function of NK cells and the accumulation of cDC1 in the TME, which are responsible for tumor immunity." (PMID 35603146, 2022). "Similar to treatment of mice with AZD5069/anti-PD1, we noted transfused immature neutrophils caused increased activation (CD86+) of intratumoural XCR1+ cDC1 cells and elevated CD8+ T cells in tumours, unlike mice transfused with equal numbers of mature neutrophils." (PMID 35477863, 2022). "Besides, no study has as yet comprehensively explored XCR1’s expression and its role in tumor development, especially its prognostic value in ccRCC." (PMID 33377624, 2021). "cDC1 express XCR1, as well as CCR1 and CCR5, both of which bind CCL5 and have antitumor functions; they can attract and activate tumor-specific CD8 T cells, and internalize and transport tumor antigens to lymph nodes, where they may cross-prime CD8 T cells." (PMID 34936871, 2021). "Further statistical results showed XCR1 expression was significantly associated with the TNM stage of ccRCC (p < 0.05, Pearson χ2 test), whereas the results related to age, gender, and tumor grade are negative." (PMID 33377624, 2021). "Moreover, they found that XCR1 alone, or with IL10, could be a potential key regulator of the tumor microenvironment, which could also represent corroborative evidence for our speculation concerning XCR1’s involvement in ccRCC." (PMID 33377624, 2021). "Interestingly, although XCR1 overexpression accentuated MDA-MB-231 cell migration, it was reported to suppress cell proliferation, tumorigenesis, and tumor growth, probably via the inhibition of MAPK activation with the reduced phosphorylation of MEK, JNK, and p38-MAPK." (PMID 33374849, 2020).